INS (insulin)
Diseases named in the same sentence as INS in open-access papers (continued):
Sharing a sentence is not in itself a finding about the gene and the disease.
diabetes (continued). "It is important to say adiponectin’s precise role in diabetes is not well characterized, although it is considered a beneficial adipokine, showing negative correlations with many age- and obesity-related diseases and a positive correlation with longevity and insulin sensitivity." (PMID 24979131, 2014). "In conclusion, the results of the present study suggest that young patients with type 1 diabetes mellitus with class II malocclusion who are not strictly monitored should not receive treatment with functional appliances until after hyperglycemia is controlled with insulin treatment." (PMID 25289023, 2014). "Since most type 1 diabetic patients are treated with insulin, it is reasonable to speculate, extrapolating from our findings that insulin lowers blood pressure in the NOD mice, that hypertension in such patients could be masked by the treatment with insulin to control diabetes." (PMID 24400109, 2014). "However, it is possible that a proportion of participants with insulin-treated T2DM have not actively managed their diabetes prior to beginning insulin, and therefore, may find some ITAS questions inappropriate." (PMID 24902877, 2014). "Diabetes mellitus (DM) is a group of metabolic diseases in which a person has high blood sugar, either because the pancreas does not produce enough insulin or because cells do not respond to the insulin that is produced." (PMID 24772443, 2014). "However, hyperglycemia, rather than growth factors such as insulin, may contribute more to mTOR activation in diabetes because mTOR is activated even in the kidneys of insulin-independent type 1 diabetic models." (PMID 25126552, 2014). "However, advanced age, COPD, and patients with insulin-treated diabetes mellitus may not benefit from BIMA grafts." (PMID 25238877, 2014). "Also, the fact that we had no information on use of diabetes technology data limits the ability to investigate whether newer technology (such as new generation of insulin pumps) may be related to mental health functioning." (PMID 25303963, 2014). "Also, we could not get the data of duration of diabetes, so we used baseline use of insulin as a covariate in the Cox regression analyses instead." (PMID 25347712, 2014). "Our results suggest that almond consumption may contribute to an improvement in cycling performance- related elements via the effect of arginine on insulin secretion and muscle glycogen synthesis without enhancing insulin sensitivity via down-regulated insulin levels noted in patients with diabetes." (PMID 24860277, 2014). "In addition, 10–30% of FRDA patients develop overt diabetes and 30% have impaired glucose tolerance, which can result from lack of insulin secretion by the insulin-producing ß cells in the pancreas, insulin resistance in muscle, liver and fat, or from a combination of both." (PMID 25198290, 2014). "Next, to examine whether hepatic insulin production induced by PDA can ameliorate blood glucose levels in the diabetic model, we injected 200 mg/kg STZ into ICR mice, followed by control Ad-GFP (n = 8) or Ad-PDA (n = 5) treatment on day 7 after diabetes induction." (PMID 25397325, 2014). "However, whether insulin use can be responsible for the diabetes-related bladder cancer is not known, and this has rarely been studied." (PMID 24466131, 2014). "In type I diabetes, or insulin dependent DM, the body has little or no insulin secretory capacity and depends on exogenous insulin to prevent metabolic disorders and death." (PMID 25070239, 2014). "The decreased insulin sensitivity is called Type 2 Diabetes Mellitus (T2 DM) or non-insulin dependent diabetes mellitus often referred to as insulin resistance." (PMID 25560330, 2014). "Interestingly, according to the National Health Interview Survey, for the past ten years the prevalence of diabetic adults who do not use insulin or oral anti-diabetic drugs to control their diabetes has slightly grown by 1% to more than 15% of US adults with diabetes." (PMID 24438493, 2014).
diabetes (continued). "Moreover, it was reported that with GH therapy, there was no increase in fasting insulin, homeostasis model assessment of insulin resistance and serum glucose level that no diabetes developed in any of the patients, but that a significant decrease was noted in serum cholesterol and LDL levels." (PMID 24932597, 2014). "Consequently, the cost of diabetes treatment strongly increases, i.e., improving coverage of the population by OAD-therapy does not only require more resources to fund OAD-drugs but also to finance insulin for the higher number of patients who survived the OAD-phase." (PMID 26208925, 2014). "Interestingly, this pathway is not inhibited in diabetes mellitus and insulin resistance; conversely, the insulin-mediated activation of eNOS viaPI3 kinase/AKT1 is inhibited, limiting its vasodilator and prosurvival function and therefore promoting vascular disease." (PMID 24734227, 2014). "For example, when counselling patients about their diabetes management options, it may be more beneficial to acknowledge, normalise and then minimise their perceived barriers to insulin use rather than emphasising only the actual benefits of insulin use." (PMID 24902877, 2014). "Moreover, insulin augmented the clearance of [3H]L-arginine from the forearm circulation in controls (baseline vs insulin: 123±22 vs. 150±28 ml/min; p<0.05) but not in diabetics." (PMID 23658699, 2013). "As ER stress is not exacerbated in high-fat-diet-induced diabetes, we suggest that failure of the islet to mount an effective adaptive UPR in response to an additional increase in insulin demand, rather than chronic ER stress, may ultimately lead to β-cell failure and hence diabetes." (PMID 24145577, 2013). "This hyperlipidemia related with diabetes mellitus may be attributed to lack of insulin." (PMID 24023648, 2013). "Diabetes mellitus (DM) is complex metabolic disorder that is characterized by a high level of blood sugar either because the body does not produce enough insulin or cells do not respond to the insulin." (PMID 24499664, 2013). "In addition, bariatric procedures can have immediate effects in lowering blood sugar levels in diabetes prior to evident changes of body weight, and this obesity-independent hypoglycemic effect has been related to the action of GLP-1 in promoting insulin section." (PMID 23700406, 2013). "Likewise, insulin sensitivity is not necessarily higher in patients with diabetes, compared to non-diabetic obese, indicating that obesity and insulin resistance likely function as environmental stressors to genuinely defective β-cells in genetically predisposed individuals." (PMID 23408938, 2013). "Interestingly, PPARG agonists have been used in the treatment of dyslipidemia and hyperglycemia and many insulin sensitizing drugs targetting PPARG are designed in the treatment of diabetes as a way to lower serum glucose without increasing pancreatic insulin secretion." (PMID 24391967, 2013). "In the context of intensive diabetes management, insulin pumps provide precise insulin delivery throughout the day and improve the accuracy of bolus dose calculations to closely follow the physiologic patterns of secretion observed in patients without diabetes." (PMID 23737776, 2013). "Physicians ́ lack of knowledge contributes to underuse of insulin and poor glycemic control in adults with diabetes mellitus (DM)." (PMID 23612462, 2013). "In Japan, a distinct subtype of T1D characterized by a rapid clinical onset (duration of symptoms before presentation and insulin treatment may be days and usually no longer than two weeks) and without islet autoantibodies has been established as fulminant type 1 diabetes mellitus (FT1DM)." (PMID 22567309, 2012).
diabetes (continued). "There are multiple sources of ROS production in diabetes including those of mitochondrial and non-mitochondrial origins; increased production of ROS and a concomitant decline of antioxidant defense mechanisms leads to damage of cellular organelles and enzymes and development of insulin resistance." (PMID 22007193, 2012). "The high agreement in diabetes may be related to patients' awareness of this condition related to self-monitoring of blood sugar and symptoms and the frequent need for oral hypoglycemic medications and insulin that have no other indication." (PMID 22448755, 2012). "However, for studies related to diabetes cellular therapy or pancreatic cancer research, the CK19+/Ca19-9+ cells arising from acinoductal transdifferentiation are of interest since they may generate insulin+ cells or cancer precursors." (PMID 22442738, 2012). "Moreover, it should be pointed out that wound closure has been evaluated in TgPED mice, which, albeit glucose-intolerant and insulin-resistant, do not display overt diabetes, raising the possibility that PED/PEA-15 effect is independent of the metabolic derangement occurring in diabetic conditions." (PMID 21780113, 2012). "The purpose of this study was to identify the origin of the insulin present in the milk of mothers with type 1 diabetes mellitus as either endogenous or exogenous by determining the levels of total insulin, endogenous insulin, and c-peptide in the milk compared to mothers without diabetes mellitus." (PMID 22500167, 2012). "If the treatment with Insulin or renal complications were considered as the indicator of severity of the diabetes, it seems that severity of the diabetes is not significantly related to self-treatment, but the symptoms that patient experience might determine his or her self-treatment behavior." (PMID 21970577, 2011). "Our findings indicate that oligomannuonate and its chromium (III) complexes improved insulin sensitivity in C2C12 skeletal muscle cells, and acted as a novel glucose uptake stimulator with low toxicity, and could be used as dietary supplementary or potential drug for type 2 diabetes mellitus." (PMID 21935427, 2011). "Diabetes Mellitus (DM) is an endocrine metabolic disorder in which the body does not produce sufficient insulin or lack of responsiveness to insulin, resulting in hyperglycemia (high blood glucose level)." (PMID 21264099, 2010). "In Europeans, who are more prone to obesity induced diabetes, blocking of GIP action on adipocytes may be more beneficial whereas it has been suggested that in Asians, GIP agonists may have a beneficial effect due to greater incidences of diabetes with impaired insulin secretion." (PMID 20673334, 2010). "While administration of STZ in rodents reliably produces hyperglycemia due to destruction of insulin secreting β-cells in pancreatic islets, other features of DM are lacking, such as immunological aspects of type 1, or insulin-resistance of type 2 diabetes." (PMID 19936237, 2009). "Thus, it is possible that those mechanisms contribute to the brain edema observed in this study; however, since lack of insulin may have consequences in terms of neuronal function, we cannot discard others inducers of brain alterations in diabetes." (PMID 19812703, 2009). "Thus, although the variations in TCF7L2 increase the risk for T2D and may affect insulin secretion, they do not alter susceptibility to FCPD, the diabetes in TCP patients." (PMID 18706099, 2008). "Abnormalities in insulin and glucagon secretion, hepatic glucose uptake, suppression of the hepatic glucose production, and peripheral glucose uptake associated with type 1 and type 2 diabetes contribute to higher and more prolonged PPBG excursions than in individuals without diabetes." (PMID 18657196, 2008).
diabetes (continued). "Insulin resistance may present without any clinical manifestation, often, many years before the appearance of frank diabetes mellitus, which would occur when the pancreas failed to secrete enough insulin to compensate such resistance and keep the person euglycemic." (PMID 15963228, 2005). "IMPROVE‐T2D showed significant early improvements in body weight, body fat, percent insulin sensitivity and secretion and glycemic control at 3 months post VSG, with most participants no longer requiring diabetes medications by 3 months following VSG." (PMID 41251158, 2026). "A KD can prevent diabetes-derived macrosomia by reducing beta cell stimulation and through insulin-independent mechanisms, but cannot reverse IUGR, warranting further studies of its role in diabetes during pregnancy." (PMID 42265456, 2026). "Type 1 diabetes mellitus (T1DM) is a chronic, non-preventable, and incurable disease that requires lifelong insulin administration." (PMID 42187921, 2026). "Using hierarchical cluster analysis, we analyzed insulin secretion, clearance and resistance in a cohort of 953 participants from the PREVADIAB2, previously enrolled in PREVADIAB1 without diabetes." (PMID 41133433, 2026). "In the general population of patients with diabetes, the most common precipitating factors for DKA are inadequate insulin therapy (often due to nonadherence) and infection." (PMID 40940823, 2025). "Despite the incidence of immune checkpoint inhibitor-induced type 1 diabetes mellitus (ICI-T1DM) is rare, the development of ICI-T1DM, especially type 1 diabetic ketoacidosis is life-threating without blood glucose monitoring and insulin therapy." (PMID 40115026, 2025). "Unlike GLP-1 receptor agonists, which enhance insulin secretion and sensitivity, SGLT2 inhibitors complement diabetes management by reducing glucose reabsorption in the kidneys, promoting glycosuria, and subsequently lowering blood glucose levels." (PMID 40004240, 2025). "The insulin-treated patients showed, also after adjustment for confounders, a statistically higher rate of MACE than patients without diabetes (31.3 % vs. 16.4 %, HR: 2.00 95 % CI: 1.29–3.12, p = 0.002)." (PMID 40687396, 2025). "Patients with diabetes not treated with SGLT2 inhibitors (e.g., on other antihyperglycemic agents or insulin)." (PMID 41170216, 2025). "Metformin, one of the primary insulin-sensitizing medications prescribed to patients with Type 2 Diabetes Mellitus (T2DM), improved memory in patients with AD and no history of diabetes or pre-diabetes." (PMID 40006083, 2025). "We performed insulin/glucagon/vimentin and SRFG staining in sections from ten organ donors without CF, diabetes or established chronic pancreatitis." (PMID 39836539, 2025). "Unfortunately, current treatment methods for children with diabetes, despite the continuous improvement of glucose control systems such as continuous glucose monitoring (CGM) or closed-loop insulin pumps, are not always sufficient to maintain normoglycemia." (PMID 40607224, 2025). "Given the obligatory role of metabolic H2O2 signaling in glucose-stimulated insulin secretion, it is not surprising that circadian clock-controlled timely suppression of oxidative stress in β-cells is crucial to the function of these cells, disruption of which may lead to diabetes." (PMID 40002419, 2025). "A recent meta-analysis shows that exercise training reduces fasting glucose, fasting insulin, and IR index (measured by HOMA-IR) in sedentary adults without diabetes." (PMID 40651083, 2025). "Non-insulin diabetes medicines are used as first-line options in the treatment of T2DM, but almost none are licensed for use in people with type 1 diabetes mellitus (T1DM)." (PMID 40651878, 2025). "Since HOMA-IR and blood glucose level increased by obesity and diabetes was not changed by QCT administration, we conclude that the QCT in our experiment did not have a major effect on systemic insulin sensitivity." (PMID 39576482, 2025).
diabetes (continued). "People with Type 2 diabetes, also called non-insulin-dependent diabetes mellitus (NIDDM), can use insulin, but their cells are not sensitive to it." (PMID 40574088, 2025). "Regarding the Mediterranean diet, the ATTICA study revealed that adherence to this dietary pattern improved fasting glucose homeostasis, insulin levels, and insulin resistance (the HOMA index) in individuals with and without diabetes." (PMID 39861488, 2025). "Type 2 diabetes mellitus (T2DM), or non-insulin-dependent diabetes, is a metabolic disorder arising from either inadequate insulin production or the body’s inability to effectively utilize insulin, also culminating in elevated blood glucose levels." (PMID 40687580, 2025). "The universal insulin requirement in this group, regardless of diabetes type, confirms that an intermediate UCPCR signifies beta-cell compromise warranting proactive management with insulin." (PMID 41180185, 2025). "IGF-1 demonstrated negative correlations with age, duration of diabetes, fasting glucose, HbA1c, total cholesterol, triglycerides, low-density lipoprotein cholesterol (LDL-C), fasting insulin, HOMA-IR, and TNF-α." (PMID 41393761, 2025). "The potential impact of newer diabetes medications, such as glucagon-like peptide 1 (GLP-1) receptor agonists and sodium-glucose co-transporter-2 (SGLT-2) inhibitors, on insulin dosage and health outcomes in these settings is not well understood." (PMID 40245017, 2025). "Over 90% of diabetes diagnoses are T2DM, a chronic metabolic disorder primarily characterized by a relative lack of insulin." (PMID 39963239, 2025). "Those with diabetes were further sub-classified into “non-insulin GLD only”, “insulin and non-insulin GLD”, or “insulin only”." (PMID 41350985, 2025). "Type 2 diabetes mellitus (T2DM), which is more common, occurs when the body does not produce enough insulin or the body's cells become insensitive to insulin." (PMID 40433165, 2025). "For patients without preoperative diabetes (IGT and normoglycaemia, n = 63), 33.3% (21/63) were discharged with diabetes therapy, including oral antidiabetic medications and insulin, after surgery." (PMID 40557340, 2025). "In this report, we describe a patient newly diagnosed with diabetes mellitus (DM) and diabetic ketoacidosis (DKA), who presented with negative insulin-related autoantibodies and no identifiable infectious etiology." (PMID 41030450, 2025). "Remission of diabetes defined as FPG < 5.6 mmol/L and an HbA1c value of ≤ 6.5% at the end of the study without taking any hypoglycemic agents including insulin." (PMID 40034634, 2025). "The most common form of diabetes is T2DM, which typically occurs in adults, where the body becomes resistant to insulin or fails to produce enough insulin." (PMID 40290901, 2025). "Some adult studies have shown short-term improvements following MBS in as little as 2 weeks postoperatively including fasting glucose, insulin, and GLP-1 and improved SI in people without diabetes." (PMID 39911520, 2025). "While all participants were insulin resistant, only one participant had diabetes, so it is not possible to make conclusions relevant to the scope of MASLD within diabetes." (PMID 40272888, 2025). "Diabetes Mellitus (DM) is a metabolic disorder of multiple etiologies, characterized and identified by the presence of hyperglycemia in the absence of treatment, due to defects in insulin secretion, insulin action, or both." (PMID 40857346, 2025). "Patients progressing to PTDM also had a clear impairment in insulin sensitivity, compared to patients in the NON-PTDM group, consistent with the concept of diabetes progression, demanding personalized, precisely tailored therapies." (PMID 38397919, 2024). "In type 1 diabetes mellitus (T1DM), the destruction of pancreatic beta cells leads to a lack of insulin production." (PMID 39479116, 2024).